RBBP4 (RB binding protein 4, chromatin remodeling factor)
Diseases named in the same sentence as RBBP4 in open-access papers (continued):
Sharing a sentence is not in itself a finding about the gene and the disease.
neurodegenerative disease (1 paper, 2024). A disorder of the central nervous system characterized by gradual and progressive loss of neural tissue and neurologic function. "Although HMGN4, KDM5D, and RBBP4 have not been directly correlated with PD, the dysregulation of chromatin-modifying complexes has been implicated in various neurodegenerative diseases, including PD." (PMID 38279299, 2024).
RBBP4 also shares sentences with these, for which no sentence is quoted: Alzheimer disease (2 papers); autoimmune (2); colorectal cancer (2); microphthalmia (2); acute lymphoblastic leukemia (1); age (1); astrocytic tumor (1); autism spectrum disorder (1); brain glioma (1); chronic myeloid leukemia (1); colorectal (1); dermatomyositis (1); developmental delay (1); Down syndrome (1); embryonal tumors (1); gliomas (1); ischemia (1); liver cancer (1); liver fibrosis (1); low grade glioma (1); lung squamous cell carcinoma (1); Lymphatic Metastasis (1); lymphoma (1); melanoma (1); metastatic cancers (1); neurodevelopmental disorder (1); Obesity (1); oropharyngeal cancers (1); primitive neuroectodermal tumor (1); Sjogren syndrome (1).
A further 4 diseases each share a sentence with RBBP4 in 1 paper.